ODAD4 (outer dynein arm docking complex subunit 4)
Description:
Component of the outer dynein arm-docking complex (ODA-DC) that mediates outer dynein arms (ODA) binding onto the doublet microtubule. Plays an essential role for the assembly of ODA-DC and for the docking of ODA in ciliary axoneme.
Synonyms: TTC25; DKFZP434H0115
Tractability: Small molecule: a structure with a bound ligand is known. Antibody: its Gene Ontology location is reachable by antibodies, with medium confidence. PROTAC: ubiquitination databases record sites on it.
Gene: Protein-coding gene on chromosome 17 (41,930,617 to 41,966,503, forward strand). Ensembl gene ENSG00000204815.
Subcellular location: Cytoplasm, cytoskeleton, cilium axoneme
Subcellular location (Human Protein Atlas): Basal body; Centrosome; Acrosome; End piece; Mid piece; Principal piece
Gene Ontology:
Molecular function: protein binding
Biological process: cilium movement; epithelial cilium movement involved in determination of left/right asymmetry; mucociliary clearance; outer dynein arm assembly; protein localization to motile cilium; flagellated sperm motility
Cellular component: 9+2 motile cilium; axoneme; cytoplasm; outer dynein arm docking complex; cilium; 9+0 motile cilium; extracellular region
Genetic constraint (gnomAD): Loss-of-function variants: 37 observed, 46.6 expected, observed/expected ratio (o/e) 0.79, 90% interval 0.61 to 1.04. The upper end of that interval is the gene's LOEUF score, 1.04, which puts it in group 4 of 6, group 1 being the genes least tolerant of losing a copy. Missense variants: 395 observed, 479.77 expected, observed/expected ratio (o/e) 0.82, 90% interval 0.76 to 0.89. Synonymous variants: 163 observed, 183.56 expected, observed/expected ratio (o/e) 0.89, 90% interval 0.78 to 1.01.
Gene-disease validity (ClinGen):
ClinGen rates the evidence that ODAD4 causes each of these diseases.
primary ciliary dyskinesia 35 (autosomal recessive): Definitive.
Homologues: Orthologues: macaque ODAD4 (96% identical), chimpanzee ODAD4 (95% identical), dog ODAD4 (80% identical), pig ODAD4 (79% identical), rat Odad4 (76% identical), mouse Odad4 (75% identical), rabbit ODAD4 (73% identical), guinea pig ODAD4 (65% identical), tropical clawed frog odad4 (47% identical), zebrafish odad4 (41% identical), Drosophila melanogaster CG13502 (15% identical).
Diseases named in the same sentence as ODAD4 in open-access papers:
ODAD4 is named in the same sentence as 13 diseases in open-access papers, as found by Europe PMC text mining. Sharing a sentence is not in itself a finding about the gene and the disease. The quoted sentences say what the papers report.
primary ciliary dyskinesia (2 papers, 2022 to 2025). A rare, genetically heterogeneous, primarily respiratory disorder characterized by chronic upper and lower respiratory tract disease. "Pathogenic variants in ODAD4 are an ultra-rare cause of primary ciliary dyskinesia (PCD)." (PMID 41002425, 2025).
bronchiectasis (1 paper, 2025). Segmental, irreversible dilation of the bronchial tree resulting in the accumulation of secretions which leads to obstruction. "Disease-causing variants in ODAD4 are a rare cause of PCD, usually resulting in classic phenotypes with lower respiratory tract infections, progressive obstructive lung disease, and bronchiectasis." (PMID 41002425, 2025). "ODAD4-associated PCD has been reported in 19 individuals thus far; all of the described cases presented with typical respiratory phenotypes and some, including affected children, with documented bronchiectasis." (PMID 41002425, 2025). "The c.234delA variant in ODAD4 seems to arise from a founder effect in French-Canadians from Quebec, and in some cases, produces a mild lower respiratory phenotype without signs of bronchiectasis or pulmonary function impairment in adulthood." (PMID 41002425, 2025).
squamous carcinoma (1 paper, 2023). "Other top genes include ODAD4, which is associated with ALL, LINC02568, which is linked to squamous carcinoma and MRPS31, which is a driver of carcinoma." (PMID 38023151, 2023).
ODAD4 also shares sentences with these, for which no sentence is quoted: asthma (1 paper); autism (1); carcinoma (1); ciliopathy (1); cyst (1); Hydrocephalus (1); lower respiratory tract infections (1); oligospermia (1); pneumonia (1); teratospermia (1).